CDC20P1 (cell division cycle 20 pseudogene 1)
Synonyms: OTTHUMG00000020142; CDC20P
Gene: Transcribed processed pseudogene on chromosome 9 (87,011,652 to 87,013,151, forward strand). Ensembl gene ENSG00000231007.
Diseases named in the same sentence as CDC20P1 in open-access papers:
CDC20P1 is named in the same sentence as 1 disease in open-access papers, as found by Europe PMC text mining. Sharing a sentence is not in itself a finding about the gene and the disease.
CDC20P1 shares sentences with these, for which no sentence is quoted: cancer (1 paper).